TMPRSS2 (transmembrane serine protease 2)
Diseases named in the same sentence as TMPRSS2 in open-access papers (continued):
Sharing a sentence is not in itself a finding about the gene and the disease.
sarcoma (7 papers, 2011 to 2022). A usually aggressive malignant neoplasm of the soft tissue or bone. "While less common than in haematological malignancies and sarcomas, recurrent gene fusions have been identified in other solid tumours, such as TMPRSS2–ERG in prostate 38 and EML4–ALK in non-small cell lung cancers." (PMID 22514011, 2012). "High NRP1 expression correlates with reduced overall survival for sarcoma (SARC), CESC, Testicular Germ Cell Tumors (TGCT) and LUSC patients in Kaplan-Meier databases, while high TMPRSS2 mRNA in tumors associates with increased survival and better prognosis for LUAD patients." (PMID 34168096, 2021).
squamous cell carcinoma (7 papers, 2019 to 2024). A carcinoma arising from squamous epithelial cells. "Chu and colleagues described the mutational characterization from whole exome sequencing of a case of PSCCT, including TMPRSS2, BRCA1, ASPSCR1, and others, but the identified driver mutations common in squamous carcinomas are absent." (PMID 36329478, 2022). "Related TTSPs, like transmembrane protease serine 2 (TMPRSS2) or human airway trypsin-like protease (HAT), and differentially expressed in squamous cell carcinoma-1 (DESC1) protein can also activate surface glycoproteins of different viruses, e.g. certain influenza viruses." (PMID 33641565, 2021).
bladder cancer (6 papers, 2020 to 2023). "The PCR signals of six genes (KLK3, TMPRSS2, KLK4, IGF1R, VEGF, and MYC) were successfully amplified in bladder cancer cell lines." (PMID 32781788, 2020). "Taken together, TPP1, TMPRSS2 and FOLR1 could all be possible prognostic markers and treatment targets in bladder cancer." (PMID 32249794, 2020).
cervical carcinoma (6 papers, 2011 to 2024). A carcinoma arising from either the exocervical squamous epithelium or the endocervical glandular epithelium. "Pseudotime series analysis showed that C0 TMPRSS2+ Tumor EPCs subgroup may be the starting point of tumor cells, and gradually differentiated into other subgroups during the progression of cervical cancer." (PMID 38482016, 2024).
esophageal cancer (6 papers, 2020 to 2023). A primary or metastatic malignant neoplasm involving the esophagus. "Similarly, we observed statistically significant positive correlation for the expression of TMPRSS2 and TMPRSS4 genes in pancreatic and esophagus cancer cell lines (d p-values < 0.05 and R-values 0.359 and 0.521, respectively)." (PMID 35970857, 2022).
head and neck cancer (6 papers, 2020 to 2023). A primary or metastatic malignant neoplasm affecting the head and neck. "The expression of TMPRSS2 is downregulated in patients with head and neck cancer, which implies more resistance to SARS-CoV-2 infection." (PMID 35281819, 2022). "In contrast, TMPRSS2 expression was downregulated in head and neck cancer and oral squamous cell carcinoma." (PMID 35017320, 2022). "Here we sought to investigate the expression of both ACE2 and TMPRSS2 in head and neck cancer specimens." (PMID 32967703, 2020).
leukemia (6 papers, 2009 to 2022). A malignant (clonal) hematologic disorder, involving hematopoietic stem cells and characterized by the presence of primitive or atypical myeloid or lymphoid cells in the bone marrow and the blood. "For example, this is the case for TMPRSS2-ERG and many leukemia-associated translocations." (PMID 21247443, 2011).
respiratory infections (6 papers, 2013 to 2025). "As a result, comprehending how TMPRSS2 interacts with viral receptors can aid in advancing these research techniques, making them critical for contending respiratory infections." (PMID 40297833, 2025). "The high expression of TMPRSS2 across multiple organs, especially the lungs, prostate, and gastrointestinal tract, may shed light on its role in the propagation and extent of respiratory infections." (PMID 40297833, 2025). "Furthermore, TMPRSS2 inhibitors might exert activity against diverse respiratory infections." (PMID 24348248, 2013).
acute myeloid leukemia (5 papers, 2014 to 2023). Acute myeloid leukemia (AML) is a group of neoplasms arising from precursor cells committed to the myeloid cell-line differentiation. "Highly immunogenic neoantigens produced by TMPRSS2::ERG2 in pancreatic cancer, DEK::AFF2 in metastatic head and neck cancer, and CBFB::MYH11 in acute myeloid leukemia have been used to generate neoantigen-reactive T-cells." (PMID 37509339, 2023).
benign prostatic hyperplasia (5 papers, 2008 to 2023). A non-cancerous nodular enlargement of the prostate gland. "The thus far reported findings of TMPRSS2-ERG in BPH (benign prostatic hyperplasia) tissue, or in a benign area from a cancerous prostate, have sometimes been speculated to result from small carcinoma foci that resided in sampled tissues and were unnoticed despite microscopic examination." (PMID 26294063, 2015). "None of the 8 normal samples and of the 11 benign prostatic hyperplasia (BPH) samples examined had evidence of the TMPRSS2: ERGa transcript." (PMID 20479932, 2010). "The relative expression of miR-34c was significantly lower in the tumor tissues compared to the benign prostatic hyperplasia (BPH) tissues, and inversely correlated with a high Gleason score, PSA level, metastatic status, survival, clinical stage, and status of TMPRSS2-ERG." (PMID 37190259, 2023).
cystic fibrosis (5 papers, 2021 to 2023). Autosomal recessive disorder caused by pathogenic variants in the CFTR gene (cystic fibrosis transmembrane conductance regulator), which encodes a chloride and bicarbonate channel expressed in epithelial cells, and follow the diagnosis criteria. "The expression rate of SARS-CoV-2 entry genes, angiotensin-converting enzyme 2 (ACE2), the main viral receptor and the proteases, furin and transmembrane serine protease 2 (TMPRSS2) in cystic fibrosis individuals is poorly known." (PMID 33401565, 2021).
dyslipidemia (5 papers, 2021 to 2023). "The TMPRSS2 rs75603675 genotype (OR = 0.586), dyslipidemia (OR = 2.289), sex (OR = 0.586), and the Charlson Comorbidity Index (OR = 1.126) were identified as the main predictors of disease severity." (PMID 35636966, 2022). "The TMPRSS2 rs75603675 genotype (OR = 2.140), dyslipidemia (OR = 2.289), sex (OR = 0.586), and the Charlson Comorbidity Index (OR = 1.126) were identified as the main predictors of disease severity." (PMID 35680409, 2022). "This translational retrospective provides novel insight into sex hormone-mediated control of TMPRSS2 in the heart and coronary vasculature in a context of existing metabolic syndrome and cardiovascular disease, suggesting further scrutiny of sex and gene-based differences is warranted." (PMID 36656980, 2023). "TMPRSS2 is a protease whose physiological function and regulation are unknown, with limited to nonexistent examinations of the impact of sex or metabolic syndrome on its regulation." (PMID 36656980, 2023).
H1N1 influenza (5 papers, 2016 to 2024). "The first study to emphasize the significance of the TMPRSS2 rs2070788 SNP in the physiological mechanisms underlying viral respiratory infections was conducted on a cohort of Asian patients infected with H1N1 influenza." (PMID 39188881, 2024). "We reported previously that Tmprss2-deficient mice are protected against H1N1 virus infections, but only marginal protection against H3N2 virus infections was observed." (PMID 26889029, 2016). "We previously showed that deletion of Tmprss2 in knockout mice strongly limits viral spread and lung pathology after H1N1 influenza A virus infection." (PMID 26889029, 2016). "TMPRSS2 gene variants has also been found to confer a twofold increase in H1N1 influenza severity supporting the hypothesis that androgen regulation of TMPRSS2 may be a critical host factor for respiratory disease." (PMID 35602518, 2022). "Similar to coronavirus models, TMPRSS2 knockout mice exhibit reduced lung pathogenesis and decreased viral spread after infection with different strains of influenza virus, including H1N1, the virus responsible for the 2009 swine flu pandemic." (PMID 33310900, 2020).
heart failure (5 papers, 2016 to 2023). Inability of the heart to pump blood at an adequate rate to meet tissue metabolic requirements. "NEW & NOTEWORTHY This retrospective analysis evaluated the impact of exercise, sex, and diet on ACE2 and TMPRSS2 mRNA levels in preclinical swine heart failure models." (PMID 36656980, 2023). "Although studies indicate exercise generally increases ACE2 levels, it is unclear if exercise of an intensity tolerable to the patient with heart failure influences genetic regulation of either ACE2 or TMPRSS2." (PMID 36656980, 2023). "This retrospective analysis presented a unique opportunity to evaluate the influence of exercise, sex, and diet on ACE2 and TMPRSS2 mRNA levels in a setting of experimental heart failure." (PMID 36656980, 2023). "The goal of this study was to determine the effects of chronic exercise training, sex, and Western diet on ACE2 and TMPRSS2 mRNA levels in preclinical swine models of heart failure." (PMID 36656980, 2023). "Unlike normal exercise intensities, exercise training of an intensity tolerable to a patient with heart failure had no influence on ACE2 or TMPRSS2 mRNA." (PMID 36656980, 2023). "Given available evidence demonstrating ACE2 levels are increased by exercise and higher in men with heart failure, we hypothesized chronic exercise training and male sex would increase ACE2 and TMPRSS2 mRNA levels." (PMID 36656980, 2023). "The current analysis supports the idea that tissue-specific differences based on sex could impact susceptibility to infection and disease severity in an experimental setting of heart failure, as ACE2 and TMPRSS2 levels differed between ventricular and coronary tissues in male and female animals." (PMID 36656980, 2023). "Surprisingly, ACE2 or TMPRSS2 mRNA was not sensitive to exercise, suggesting training intensities tolerable for a patient with heart failure may not be potent enough to induce alterations in the regulation of these genes." (PMID 36656980, 2023). "Contrary to our hypothesis, ACE2 and TMPRSS2 mRNA levels were not sensitive to a chronic exercise training stimulus tolerable to a patient with heart failure irrespective of total exercise dose or intensity." (PMID 36656980, 2023). "In addition to TMPRSS2 overexpression, two ex vivo studies comparing heart samples from patients with (n = 23 and n = 40, respectively) and without (n = 9 and n = 15, respectively) heart failure found that ACE2 was upregulated in the heart failure samples." (PMID 34269511, 2021).
neuroblastoma (5 papers, 2017 to 2024). Neuroblastoma (NB) is the most common solid, extracranial childhood tumor. "Our results indicated that SH-SY5YSY-Y5 neuroblastoma cells displayed the highest mRNA expression of ACE2 and TMPRSS2; however, they presented the lowest protein expression." (PMID 34325716, 2021). "Here, we show that SH-SY5Y neuroblastoma cells express three important cellular surface molecules that interact with the Spike protein, namely ACE2, TMPRSS2, and NRP1." (PMID 34834998, 2021). "Overall, our data clearly indicate that RA-differentiated SH-SY5Y neuroblastoma cells show an increased expression of the surface molecules used by SARS-CoV-2 to enter the cells, namely NRP1, TMPRSS2, and, to a lesser extent, ACE2." (PMID 34834998, 2021).
non-small cell lung carcinoma (5 papers, 2012 to 2022). A group of at least three distinct histological types of lung cancer, including non-small cell squamous cell carcinoma, adenocarcinoma, and large cell carcinoma. "For people with non-small-cell lung cancers, very interestingly, some of the patient-specific cell groups, which might be from the tumor heterogeneity, showed considerable expression of TMPRSS2, with the ACE2 level unknown due to the prefiltering of the data." (PMID 32973879, 2020). "Examples of fusion genes discovered with the help of modern genomics include: the TMPRSS2-ERG in prostate cancer, RET-CCDC6 in thyroid carcinoma, and EML4-ALK in non-small cell lung cancer (NSCLC)." (PMID 33946483, 2021).
renal carcinoma (5 papers, 2020 to 2023). A carcinoma arising from the epithelium of the renal parenchyma or the renal pelvis. "The expression of TMPRSS2 in cancerous kidney cell lines, such as those found in renal carcinoma tissues can vary." (PMID 38255667, 2023). "Immunohistochemical analysis of these coronavirus receptors revealed that TMPRSS2 levels decrease during renal carcinoma as compared to normal renal tissues." (PMID 33330620, 2020). "We further analyzed the expression of ACE2, ANPEP, ENPEP, DPP4, and TMPRSS2 gene in renal carcinoma tissues." (PMID 33330620, 2020). "It would also be interesting to evaluate this possibility of mechanism in renal cancer where the general expression of TMPRSS2 does not seem to be so high." (PMID 38255667, 2023). "Therefore, it is essential to investigate the function of ACE2 and TMPRSS2 in RCC, and their potential prognostic impact on patients with renal cancer after COVID-19 infection." (PMID 34131396, 2021). "In addition, the emerging findings investigating the clinical implications of ACE2, TMPRSS2, and NRP1 expression on renal cancer cells for RCC treatment, and the prognostic significance of gene signatures related to SARS-CoV-2 infection in renal cancer cell patients will be reviewed." (PMID 38255667, 2023). "Our results revealed that TMPRSS2 may not be the co-receptor for coronavirus infection in renal carcinoma patients." (PMID 33330620, 2020). "We found evidence that TMPRSS2 may not be the auxiliary protein for SARS-CoV-2 or any coronavirus infection in renal carcinoma." (PMID 33330620, 2020). "Interestingly, emerging evidence suggests that the retained expression of angiotensin-converting enzyme 2 (ACE2), transmembrane serine protease 2 (TMPRSS2), and neurolipin 1 (NRP1) on the renal cancer cell could increase tumor immunogenicity and promote a cytolytic effect." (PMID 38255667, 2023).
small cell carcinoma (5 papers, 2011 to 2020). A neuroendocrine carcinoma composed of small malignant cells which are often said to resemble "oat cells" under the microscope. "Interestingly, the genomic loss at the TMPRSS2 locus was present in two CRPC patients with a pathological diagnosis of small cell carcinoma (neuro-endocrine origin)." (PMID 25915538, 2015). "As compared to small-cell prostate carcinoma, the TMPRSS2-ERG gene fusion is frequently absent in any small cell carcinoma of the urinary bladder or lung; this can aid in differentiating small cell carcinoma of prostatic origin from non-prostatic origins." (PMID 32764454, 2020). "TMPRSS2-ERG fusion gene is generally used in the diagnosis of small cell carcinoma of prostate rather than bladder." (PMID 26788399, 2015).
breast invasive cancer (4 papers, 2014 to 2022). "The ERG-induced mesenchymal-like signature positively correlated with TMPRSS2-ERG prostate tissues and invasive breast cancer mRNA expression datasets reflecting a general ERG-driven pattern of malignancy." (PMID 24504051, 2014).
chronic lung disease (4 papers, 2020 to 2025). According to the definitions of the American and British Thoracic Societies, including pulmonary functional tests, X-rays, and CT scans for items such as fibrosis, bronchiectasis, bullae, emphysema, nodular or lymphomatous abnormalities. "In the future, it is worthwhile to look into the retention of the FCS site in HAE-ALI cultures derived from donors of different sexes, age groups, and other chronic lung diseases, as well the expression levels of the cellular proteases furin, TMPRSS2, and cathepsin in these HAE-ALI cultures." (PMID 33975939, 2021).
coagulopathy (4 papers, 2020 to 2025). "When specifically focusing on cancer, ACE2 and TMPRSS2 expression is found higher in cancer patients, and coagulopathy is a potential risk observed in a number of cancer patients." (PMID 34090396, 2021).
emphysema (4 papers, 2020 to 2023). "The viral entry depends on TMPRSS2 protease activity, and a higher expression was detected in elderly smokers and ex-smokers and emphysema patients." (PMID 34356843, 2021). "Together, our results suggest that high ACE2 and TMPRSS2 expression in individuals with emphysema may increase the SARS-CoV-2 infection rate." (PMID 34356843, 2021). "Also, we detected increased TMPRSS2 protein expression in emphysema patients compared to controls." (PMID 34356843, 2021). "We compared TMPRSS2 gene and protein levels in ATII cells isolated from non-smokers, smokers, young, elderly, and emphysema patients." (PMID 34356843, 2021).
invasive carcinoma (4 papers, 2016 to 2024). A carcinoma that is not confined to the epithelium, and has spread to the surrounding stroma. "Consequently, they proposed a retrograde colony formation model wherein the TMPRSS2-ERG fusion gene-positive/PTEN loss component of invasive carcinoma infiltrates normal glandular ducts, forming IDCPs." (PMID 38732035, 2024). "TMPRSS2:ERG fusion is known to play a critical role in driving the progression from prostatic intraepithelial neoplasia (PIN) to invasive carcinoma." (PMID 36980776, 2023). "TMPRSS2‐ERG fusion rates are similar between IDC‐P and concurrent invasive carcinoma." (PMID 38379333, 2024).
kidney cancer (4 papers, 2020 to 2022). Primary or metastatic malignant neoplasm involving the kidney. "Although some studies have explored the function of ACE2 in pan-cancer 21 and clear cell RCC (ccRCC) 22, studies on ACE2 and TMPRSS2 in kidney cancer remain scarce." (PMID 34131396, 2021). "We found that LSD1 binds to AR target genes including KLK2, KLK3, and TMPRSS2 in kidney cancer cells, and confirmed that the binding decreased in LSD1 shRNA-expressing cells." (PMID 32847068, 2020). "However, the functions of ACE2 and TMPRSS2 in kidney cancer remain unclear, especially as kidneys are targets for SARS-CoV-2 infection." (PMID 34131396, 2021). "We applied multi-omics tools to explore the role of ACE2 and TMPRSS2 in KIRC and KIRP and evaluated the impact of COVID-19 infection in kidney cancer patients." (PMID 34131396, 2021).
Middle East respiratory syndrome (4 papers, 2021 to 2023). A viral respiratory infection that is caused by the MERS coronavirus (MERS-CoV), which most often manifests with moderate to severe respiratory symptoms, including productive cough and shortness of breath, which can progress to pneumonia and acute respiratory distress syndrome. "It has been shown that TMPRSS2−/− mice not only are resistant towards IAV and CoV infection, including SARS-CoV and Middle East respiratory syndrome (MERS), but also show different immunopathology and reduced inflammatory lesions." (PMID 36830955, 2023).
oral squamous cell carcinoma (4 papers, 2020 to 2022). "It was observed that in the human epithelial‐like oral squamous cell carcinoma cell lines HSC2, HSC3, and HSC4 gene expression of ACE2 was present in HSC3 while the gene expression of TMPRSS2 was present in HSC4." (PMID 33421967, 2021).